STAT3 (signal transducer and activator of transcription 3)
Diseases named in the same sentence as STAT3 in open-access papers (continued):
Sharing a sentence is not in itself a finding about the gene and the disease.
Insulin resistance (continued). "The previous studies indicated that metformin and bromocriptine might alleviate hepatic insulin resistance through modulating the STAT3-dependent pathway, insulin sensitivity, and gluconeogenesis." (PMID 35956419, 2022). "The Janus kinase (JAK)/STAT3 pathway as well as the activation of STAT3 through AKT kinase and mTOR are the important insulin/IGF-1-stimulated, STAT3-mediated signaling pathways which are able to control immunosuppression, immunosenescence, and insulin resistance." (PMID 34476533, 2021). "Moreover, STAT3 is recognized as a key regulator of insulin resistance and conducts the regulation of appetite and energy metabolism by monitoring the transcription of downstream target genes." (PMID 33833859, 2021). "Notably, IL6, NFKBIA, NFKB1, NOS3, PTPN1, PIK3R1, and STAT3 (members in the enriched WGCNA module) have been shown to alter insulin resistance." (PMID 33005175, 2020). "Yu’s study has found that up-regulation of the NF-kB and STAT3 signaling pathway could promote insulin resistance in liver cells which was potent for NAFLD prevention." (PMID 32863886, 2020). "Importantly, IL-6/STAT3 signaling was shown to regulate the depressive behavior as well as the process of insulin resistance." (PMID 32655424, 2020). "Moreover, pu-erh tea ameliorated insulin resistance by inhibiting IL-6 induction via signal transducer and activator of transcription 3 (STAT3) in C57BL/6J mice." (PMID 32294991, 2020). "Moreover, the hyperactivated STAT3 induces the suppression of the 3-phosphoinositide pathway and, as a result, provokes the leptin and insulin resistance in the hypothalamus, as was shown in mice expressing a constitutively active STAT3 in the POMC-neurons." (PMID 30870482, 2019). "In fact, modulation of the IL-6/STAT3 hepatic signaling pathway has been proposed as the underlying mechanism accounting for the beneficial effects of Pu-erh tea extract on HFD-induced NASH and insulin resistance." (PMID 30818779, 2019). "Previous studies have demonstrated that STAT3 absence in hepatocytes may result in insulin resistance and augmented expression of gluconeogenic genes, mediated by the dysregulation of IL-6 signaling." (PMID 30205811, 2018). "Further studies are essential to firmly establish the unknown factors involved in the IL-15-Jak3/STAT3 signaling axis for the potential treatment and/or prevention of metabolic disorders, such as insulin resistance or diabetes." (PMID 28066259, 2016). "In addition, IL-6 appears to be directly involved in the activation of NF-kB/STAT-3 and insulin resistance." (PMID 25338520, 2014). "Of particular relevance to DIO and insulin resistance is STAT3." (PMID 15985155, 2005). "STAT3 may be involved in nutrition induction and cytokine-induced insulin resistance." (PMID 39950110, 2025). "Therefore, SEA may contribute to the induction of insulin resistance and diabetes by inducing STAT3 phosphorylation." (PMID 37110462, 2023). "In addition, Aβ induced insulin resistance by activating the JAK2/STAT3/SOCS-1 signaling pathway." (PMID 37033452, 2023). "However, Jamshidi and other studies found that SNP rs2293152 of the STAT3 gene was associated with insulin resistance, but it has not confirmed its association with the occurrence and development of type 2 diabetes." (PMID 33833859, 2021). "The SphK1/S1PR1/STAT3 axis may enhance and amplify insulin resistance." (PMID 34751249, 2021). "Interestingly, activated STAT3 signaling has been involved in insulin resistance." (PMID 27101310, 2016). "Metformin use may reduce inflammation in patients with diabetes either through the improvement of metabolic disturbances such as hyperglycemia, insulin resistance and dyslipidemia or through its inhibition of the proinflammatory cancer-promoting nuclear factor κB and STAT3 pathways." (PMID 26683519, 2016). "Interestingly, STAT3 also contributes to insulin resistance and glucose homeostasis." (PMID 27519769, 2016).
Insulin resistance (continued). "Furthermore, the data are supported by STAT3 manipulation models of mice showing that liver specific knock-out induces neoglucogenic gene expression and hepatic insulin resistance, whereas liver specific overexpression of STAT3 reduces glycemia, insulinemia and neoglucogenic gene expression." (PMID 24410832, 2014). "Hence reduced STAT3 signaling secondary to insulin resistance in the offspring of SF dams might be expected to reduce activity in the obese/hyperleptinaemic females, and shall be further explored." (PMID 23423541, 2013). "Regarding insulin resistance, activation of PPARD has been reported to improve high-fat diet-induced insulin resistance via the IL-6/signal transducer and activator of transcription 3 pathway by increasing AMP-activated protein kinase activity in mice." (PMID 39899669, 2025). "The activation of STAT3 stimulates the secretion of IL-6 and activates JNK, mTOR, and protein kinase C (PKC) signaling pathways, which aggravate insulin resistance." (PMID 40863244, 2025). "As an upstream target of FOXO4, IL6/STAT3 signaling activation promotes insulin resistance in adipose tissue and muscle, and JAK2/STAT3 activation induces insulin resistance in HepG2 cells." (PMID 41573199, 2025). "Specifically, regarding genes related to insulin resistance pathway, we highlight SOCS3, GSK3B, STAT3, PTEN, TRIB3, FOXO1, and PTPRF, along with MAPK8, which plays a role in metabolic stress and inflammation." (PMID 41282288, 2025). "Recent reviews also indicate that anthocyanins regulate leptin signaling by increasing ObR receptor expression and activating the JAK2/STAT3 and PI3K/Akt pathways, which improves leptin sensitivity and reduces insulin resistance." (PMID 41374016, 2025). "Collectively, these findings suggest that hepatitis viruses promote insulin resistance and type 2 diabetes mellitus (T2DM) through STAT3-dependent mechanisms, including IRS functional inhibition, ubiquitin-mediated degradation, and metabolic reprogramming." (PMID 40918255, 2025). "TNF can activate STAT3, HIF-1a, Th17, and IL-6, while IL-1 can induce insulin resistance, HIF-1 production, and JAK-STAT signals." (PMID 39891057, 2025). "In our study, CDD effectively improved body weight, insulin resistance index, and ovarian function in PCOS-IR model mice, and significantly downregulated both mRNA and protein expression levels of the IL6/JAK2/STAT3/FOXO4 signaling pathway." (PMID 41573199, 2025). "Pelargonic acid vanillylamide (PAVA) alleviates NAFLD by exhibiting anti-inflammatory effects and improving insulin resistance mediated by the Janus kinase 2 (JAK2)/signal transducer and activator of transcription 3 (STAT3) pathway." (PMID 39281271, 2024). "To investigate the mechanism by which α7nAchR activation prevents insulin resistance, we also evaluated the ability of PNU to prevent insulin resistance after pharmacological inhibition of α7nAchR and its downstream effectors JAK2 and STAT3." (PMID 35883638, 2022). "Evidences indicate that insulin resistance can impact the increase of IL-6, and in TLRs, more specifically, type 4 (TLR-4), these mechanisms aremediated by the STAT3 pathway in skeletal muscle." (PMID 35052633, 2022). "Several studies have investigated the relationship between STAT3 activation and insulin resistance, indicating mediation between specific tissues (hepatic and muscle), cytokines (IL-6), and adipokines (visfatin), in addition to the signpost SOSC3/STAT3." (PMID 35052633, 2022). "Accordingly, the mTOR/STAT3 pathway controls several important downstream targets, such as HIF-1α and Notch1, which are involved in the regulation of insulin resistance." (PMID 34476533, 2021). "It seems that inflammaging stimulates JAK/STAT3 signaling which augments the expression of SOCS proteins and subsequently promotes cellular senescence and insulin resistance in a cell-type dependent manner." (PMID 34476533, 2021).
Insulin resistance (continued). "And most importantly, STAT3 played a core role in enriched KEGG pathways, including AGE-RAGE signal, FoxO signal, HIF-1 signal, and insulin resistance." (PMID 34512330, 2021). "Catechins from oolong tea can alleviate ovarian dysfunction and insulin resistance in PCOS mice by inhibiting uterine inflammation and matrix degradation via inhibiting p-STAT3 signaling." (PMID 33292347, 2020). "We first examined the effects of a specific inhibitor of JAK2/STAT3, AG490, and a specific NF-κB inhibitor, BAY11-7082, on the visfatin-induced expression of inflammatory cytokines and insulin resistance in HepG2 cells." (PMID 31396538, 2019). "To elucidate the probably mechanism on the effect of insulin resistance HUVEC cells induced by miR-492, we characterized STAT3, SOCS3, and P-selectin expression in the insulin resistance HUVEC cells transfected with miR-492 mimics or pre-scramble for 48 h." (PMID 24526524, 2014). "Activation of PPAR-β/-δ with agonist prevents induction of the transcription factor STAT3 by inhibiting the activation of ERK and inhibiting the interaction of STAT3 and Hsp90; this translates into the prevention of insulin resistance in adipose tissue." (PMID 23781121, 2013). "Furthermore, STAT3 inhibits the phosphorylation of insulin receptor substrates (IRS) by up-regulating SOCS3, exacerbates insulin resistance, and forms a vicious cycle of metabolism and inflammation." (PMID 41226680, 2025). "Inhibits digestive enzymes, modulates neurohormones, improves gut microbes, boosts BAT activity, inhibits fat formation (Wnt, Rb), alleviates insulin resistance (PI3K/AKT, STAT3), anti-inflammatory (COX-1, COX-2, MMP), attenuates muscle atrophy (p38 MAPK, ubiquitination), mitochondrial protection." (PMID 41404330, 2025). "This suggests that granulosa cell knockdown of STAT3 does not affect the overall amelioration of insulin resistance by IL-22." (PMID 38734641, 2024). "Risperidone could reduce both leptin-induced signal transducer and activator of transcription 3 (STAT3) phosphorylation and insulin-mediated protein kinase B activation, which could result in LEP and insulin resistance." (PMID 38375208, 2023). "Knockout of the FGF21 gene in liver tissue can activate glucose-6-phosphatase and phosphoenolpyruvate carboxykinase through STAT3/SOCS3 pathway, thus increasing gluconeogenesis and glycogen decomposition, resulting in the aggravation of liver insulin resistance." (PMID 36982739, 2023). "Lack of STAT3 in hepatocytes can also lead to increased insulin resistance and increased expression of gluconeogenesis-related genes." (PMID 37404827, 2023). "In addition, STAT3 induces TLR4 production and further regulates proinflammatory cytokines and insulin resistance in myoblasts." (PMID 35563546, 2022). "Signal transducer and activator of transcription 3 (STAT3) is involved in cytokine insulin resistance, but its role in muscle insulin resistance and diabetes is not completely clear." (PMID 35154608, 2021). "Importantly, we demonstrated that the continuing healthcare benefit of catechins extract was to rescue hormonal disorders, insulin resistance, and ovarian and uterine pathological changes of PCOS mice by inhibiting STAT3 signaling in the uterus." (PMID 33292347, 2020). "Then, it is reasonable to speculate that IL-13 plays a protective role in insulin resistance by promoting IRS-1 and AKT phosphorylation in insulin-dependent tissues via STAT3 and STAT6 activation as well as improvement of the beta-cell function." (PMID 29675435, 2018). "M2 macrophages are responsible for maintaining the adipose tissue in an insulin sensitive state, through the anti-inflammatory action of IL-10 and signal transducer and activator of transcription 3 (STAT3) pathways, whereas M1 secrete pro-inflammatory cytokines contributing to insulin resistance." (PMID 27128935, 2016).
Insulin resistance (continued). "The Cytoplasmic Polyadenylation Binding Protein (CPEB) interacts with mRNA to control translation; knockout mice that lack CPEB exhibit high-fat-diet-induced liver insulin resistance and do so by having aberrant expression of major insulin signaling molecules, in particular PTEN 3 and Stat3." (PMID 22253608, 2012). "Additionally, dendrobine might affect cell signal transduction by influencing genes like AKT1, STAT3, potentially related to KEGG pathways such as “insulin resistance”, “PPAR signaling pathway”, and “insulin signaling pathway”." (PMID 38755697, 2024). "Mechanistically, STAT3-AR co-binding stimulated by CCRK transcriptionally activates its own promoter, which in turn triggers the mTORC1/4E-BP1/S6K/SREBP1 cascades via GSK3β phosphorylation to augment hepatic lipid accumulation, glucose intolerance, insulin resistance, and tumorigenicity." (PMID 30523261, 2018). "In contrast, mice with Stat3−/− myeloid cells did not develop HFD-induced hyperglycemia and hyperinsulinemia, insulin resistance, and glucose tolerance." (PMID 40801626, 2025). "It seems that while the negative feedback of the STAT3 signaling delays the insulin/IGF-1-induced aging process, it nonetheless elicits insulin resistance and diabetes." (PMID 34476533, 2021). "Despite the lack of direct binding, STAT3 is still retained as a core target because it plays a core role in the PPI network (degree = 49, ranking first in connectivity) and participates in the insulin resistance process through signaling pathways such as insulin resistance and HIF-1." (PMID 40508108, 2025).
diabetes (166 papers, 2005 to 2026). "On the other hand, in a previous study that analyzed monogenic diabetes in 64 patients diagnosed before 1 year of age, a mutation causing monogenic autoimmunity was found in 2 patients, 1 in STAT3 and the other in FOXP3." (PMID 39870583, 2025). "As OB mice are leptin-deficient, we propose a leptin-independent mechanism of STAT3 activation, which is mediated via macrophages in this diabetes-resistant mouse strain." (PMID 39508880, 2025). "HBV-induced liver cirrhosis patients exhibit elevated levels of S100A8/A9, natural killer (NK) cells, and interferon-gamma (IFN-γ) following STAT3 activation, a biomarker profile associated with diabetes development." (PMID 40918255, 2025). "Lastly, STAT3 expression has been associated with β-cell dysfunction and promotion of neonatal diabetes." (PMID 38326874, 2024). "Diabetes was the earliest endocrine manifestation in early‐onset multiorgan autoimmunity cased by STAT3 GOF variants." (PMID 38404237, 2024). "To date, the few studies conducted has been limited to individuals with diabetes mellitus who have a specific missense variant in the STAT3 gene, and the functional validation of human pancreatic β‐cells is lacking." (PMID 38404237, 2024). "The impact of STAT3 GOF variants on diabetes outside of the immune system has yet to be investigated further in human pancreatic β‐cells." (PMID 38404237, 2024). "In conclusion, we can say that ginsenoside Rg1 inhibits STAT3 expression by miR-15b-5p to attenuate lung injury in mice with type 2 diabetes mellitus-associated pulmonary tuberculosis." (PMID 36248428, 2022). "Gain of function STAT3 mutations have been shown to promote diabetes, while inhibition of the JAK kinase upstream of STAT3 has been shown to control lymphoproliferation in a diabetes patient with a STAT3 gain of function mutation." (PMID 35328698, 2022). "The phenotypic shift of vascular smooth muscle cells in diabetic animal models is caused by the RAGE/JAK2/STAT3 pathway in the maintenance of diabetes-mediated circulatory problems through the modification of kinetics in mitochondria." (PMID 36497125, 2022). "The IL-6/JAK/STAT3 signalling pathway is implicated in various diseases including cancer and diabetes." (PMID 35562959, 2022). "Based on serial drug level determination and functional assays, 8-h dose intervals have been recently suggested in a child with STAT3 GOF mutation associated with immune dysregulation (type 1 diabetes mellitus and interstitial lung disease)." (PMID 35486339, 2022). "Predisposing factors included the use of immunosuppressants, solid organ transplantation, mutations in the CARD9 or STAT3 (signal transducer and activator of transcription 3) genes, diabetes, and trauma." (PMID 34436168, 2021). "It is difficult to assess the role of JNK1 and Stat3 in the diabetes‐associated centrosome amplification in vivo." (PMID 30478982, 2019). "STAT3 is over-expressed in endometrial cancer, and diabetes is a risk factor for the development of type 1 endometrial cancer." (PMID 28114390, 2017). "In summary, this study demonstrated that, in the late stage of STZ-induced diabetes, rats displayed the inactivation of STAT3, APN deficiency, and the increase of FoxO1 and CD36 expression." (PMID 26783539, 2016). "In the present study, we found that, in the late stage (8 weeks of diabetes) of STZ-induced diabetes, rats displayed the inactivation of STAT3, APN deficiency, and the increase of FoxO1 and CD36 expression." (PMID 26783539, 2016). "These include transcription factors concerned with the control of: adipogenesis (Pparγ, Klf15, Irf1, Creb1, Egr2, Gata3); lipogenesis (Mlxipl, Srebp1c); inflammation (Jun, Stat3); insulin signalling and diabetes susceptibility (Foxo1, Tcf7l2)." (PMID 21187013, 2010).